IL5 (interleukin 5)
Diseases named in the same sentence as IL5 in open-access papers (continued):
Sharing a sentence is not in itself a finding about the gene and the disease.
asthma (continued). "For a long time, inflammatory diseases were thought to associate with either an IFNγ-driven Th1-type inflammatory response (e.g. multiple sclerosis) or a Th2-type response characterised by the expression of IL-4, IL-5 and IL-13 (e.g. asthma)." (PMID 35275333, 2023). "In the present study, we retrospectively evaluated the efficacy and safety of these anti-IL-5/IL-5Rα mAbs in 29 Japanese patients with asthma-complicated ABPA." (PMID 37015988, 2023). "Th2 cytokines, including interleukin (IL)-5, IL-4, and IL-13 play a significant role in initiating the inflammatory cascade in asthma." (PMID 37063828, 2023). "Based on accumulating evidence implicating IL-4, IL-5, and IL-13 are responsible for the occurrence and development of asthma." (PMID 37377958, 2023). "IL-5 is critical in the pathogenesis of asthma, eosinophilic granulomatosis, and eosinophilic chronic rhinosinusitis." (PMID 37885900, 2023). "Several biological agents, including anti-immunoglobulin E, anti-interleukin-5, and anti-thymic stromal lymphopoietin/interleukin-4, have been approved for the treatment of severe asthma." (PMID 38203353, 2023). "EDN over peripheral blood eosinophil count is recommended to monitor the asthma control status and to assess the efficacy of anti-IL-5 therapy in asthma." (PMID 37174726, 2023). "JAK inhibitors are an attractive small molecule option given the widespread signaling of cytokines and growth factors using JAK-STAT receptors in asthma, including IL-4, IL-5, IL-13, GM-CSF, IFN-α, IFN-β, IFN-γ, and TSLP." (PMID 37265457, 2023). "High serum concentrations of IL-5 can be detected in patients with severe asthma, even if eosinophilopoiesis takes place in these subjects not only in the bone marrow, but also within the airways." (PMID 37240477, 2023). "Approximately 50% of patients with severe asthma have eosinophil-dominated airway inflammation and elevated type 2 (T2) responses (e.g. IL-4, IL-5, IL-13, immunoglobulin [Ig]E levels)." (PMID 38044426, 2023). "It is believed that IL-5 and IL-13 play important roles in the etiology of asthma, with IL-13 acting on a different pathway from IL-5 to cause airway hyperreactivity (AHR) in the allergic lung." (PMID 37239461, 2023). "A recent study highlighted the major contributions of Th2 cytokines, such as IL4, IL13, and IL5, to asthma, while interferon-γ, a Th1 cytokine, has recently been shown to maintain the chronic inflammatory response in asthma." (PMID 37191813, 2023). "Novel saliva biomarkers, such as eotaxin, IL-5, and IL-8, are easier to collect and have shown a strong correlation with the level of asthma control, but their role is still to be determined." (PMID 38248721, 2023). "Three biologics, namely benralizumab, mepolizumab, and reslizumab, have received approval within the IL-5 class of anti-asthma drugs." (PMID 38004421, 2023). "Whereas total Tc/Th cell frequencies were similar between asthma patients and HCs, production of the type-2 cytokines IL-5, IL-9, and IL-13 by both Tc and Th cells was significantly higher in asthma patients than in HCs." (PMID 37612281, 2023). "Upon exacerbating, asthma patients showed significantly decreased frequencies of IFNγ+ and simultaneously increased frequencies of IL-4+, IL-5+, and IL-9+ Tc and Th cells." (PMID 37612281, 2023). "Mepolizumab, an anti-IL-5 monoclonal antibody, reduces blood eosinophil counts, and its efficacy in severe asthma has been established in large-scale trials." (PMID 37179316, 2023). "Mepolizumab was effective in severe asthma with bronchiectasis, suggesting emerging phenotype responsive to anti-IL-5." (PMID 38161547, 2023). "The importance of type 2 inflammation in asthma is highlighted by the effectiveness of biologic therapies that target and inhibit IL-4 and IL-5 signaling pathways." (PMID 37047327, 2023).
asthma (continued). "Persistent inflammation in allergic disorders i.e. rhinitis, asthma etc. is maintained by multiple cytokines (IL-4, IL-5 and IL-13) released from Th2 cells followed by mast cell degranulation, infiltration of inflammatory cellsand excessive mucus secretion." (PMID 37316684, 2023). "T-helper 2 (Th2) and type 2 (T2) innate lymphoid cells (ILC2) orchestrate the inflammatory process in asthma through the secretion of Th2 cytokines (IL-4, IL-5, and IL-13), promoting eosinophilic inflammation in the airway mucosa." (PMID 37627282, 2023). "Further discrepancies between COPD and asthma have been observed when evaluating treatment responses to therapies directed against IL-5, which have been shown to be effective in severe eosinophilic asthma." (PMID 37371101, 2023). "Previous studies found that vitamin D supplementation can reduce the levels of IL-5 in patients with asthma and COPD." (PMID 37705107, 2023). "Once stimulated, ILC2 and Th2 produce type 2 cytokines, including IL-4, IL-5, and IL-13, responsible for the main alterations present in asthma." (PMID 37947596, 2023). "Lycopene exerts a therapeutic effect against asthma by reducing eosinophilic infiltrates and Th2-mediated cytokines IL-4 and IL-5 production in the airways." (PMID 37367073, 2023). "Targeting IL-5 or IL-5Rα, the main mediators of eosinophilic inflammation, through monoclonal antibodies can reduce eosinophilia in severe asthma patients with uncontrolled symptoms." (PMID 38259298, 2023). "ALA has been demonstrated to drastically lower serum IgE concentration, attenuate Th2 cytokines, IL-4, IL-5, IL-13, and IL-18, and reduce NF-B activation by decreasing intracellular ROS levels in a mouse model of asthma with allergic airway inflammation." (PMID 37251328, 2023). "For example, studies have shown the efficacy of biologicals targeting interleukin-5 (IL-5) and interleukin-4/13 (IL-4/13) in asthma and the effectiveness of nintedanib, a tyrosine kinase inhibitor, in slowing the progression of IPF." (PMID 37631365, 2023). "In induced sputum, IL-5 levels were found to be inversely correlated with apoptotic eosinophils in patients with either stable asthma or acute disease exacerbations." (PMID 37240477, 2023). "Anti-IL-5 therapy is indicated for eosinophilic diseases, such as asthma, eosinophilic granulomatosis with polyangiitis, and eosinophilic chronic rhinosinusitis, and blood eosinophil count is the best-established biomarker for the prediction of its efficacy." (PMID 36732834, 2023). "As rBmTI-A reduced the concentrations of IL-5, IL-10, IL-13, and IL-17A, CrataBL reduced the numbers of IFN-γ, IL-4, IL-5, IL-13, and IL-17 positive cells in the airways and alveolar walls; both studies used an asthma model." (PMID 37511021, 2023). "As mentioned, CRSwNP has been considered an indicator to predict the response to anti-IL-5 antibodies in T2 asthma." (PMID 37509606, 2023). "Here we provide compelling evidence that the Tc cell compartment in asthma undergoes substantial phenotypic skewing, resulting in a functional shift away from type-1 (e.g., IFNγ) and towards type-2 (e.g., IL-5, IL-9) cytokine production." (PMID 37612281, 2023). "Derangements of Th cells are deeply involved in the pathogenesis of asthma, in which Th2-secreted cytokines such as IL-4, IL-5 and IL-13 promote the accumulation of eosinophils and Th17-produced IL-17 mediate neutrophil recruitment." (PMID 37449208, 2023). "Biologics, such as dupilumab (anti-IL4Rα) and mepolizumab (anti-IL-5), improve lung function and reduce exacerbation frequency in patients with asthma." (PMID 37047327, 2023). "Most patients with asthma have T2 inflammation, characterized by cytokines (IL-4, IL-5, and IL-13) and inflammatory cells (eosinophils, mast cells, basophils, and IgE-producing plasma cells)." (PMID 38203353, 2023). "Three anti-IL-5 biologicals and one anti-IL-4R biological have recently emerged as promising treatments for type 2 (T2) asthma." (PMID 37631365, 2023).
asthma (continued). "In DREAM (Dose Ranging Efficacy and Safety with Mepolizumab) study in severe asthma reported that the use of anti-IL-5 represented an important treatment option in patients with severe eosinophilic asthma." (PMID 37259416, 2023). "Th2 cells secrete IL-4 and IL-5 and increase IgE levels and eosinophil numbers, which can trigger inflammation, leading to asthma." (PMID 37569643, 2023). "By blocking IL-5, mepolizumab can reduce the number of eosinophils in the blood and airways, which can significantly reduce asthma exacerbations and improve lung function in children with severe asthma, particularly those with high levels of eosinophils." (PMID 37685533, 2023). "MIP‐1 beta is a type 1 associated cytokine; in adult asthma patients, a higher MIP‐1 beta level has been associated with a poorer response to anti‐IL‐5 therapy." (PMID 38006383, 2023). "The changes of peripheral CD3−CD56+CD16+ NK cells proportions positively correlated with the IFN-γ/IL-4 and IFN-γ/IL-5 ratios on day 1 to day 3 in asthma subsequent to upper respiratory viral infections." (PMID 37865742, 2023). "Administration of VD to VD-deficient mice with asthma reduces BALF levels of neutrophil, eosinophil, IL-5, and IL-13." (PMID 37367073, 2023). "Th2 cells, which produce IL-4, IL-5, and IL-13 in an antigen-dependent manner, are thought to play a major role in the pathogenesis of asthma." (PMID 37377958, 2023). "T helper 2 cells (Th2), as a primary source of the type 2 cytokines IL-4, IL-5, and IL-13, capable of driving all these immunological and physiological features, have therefore long been considered central to asthma pathogenesis." (PMID 37163370, 2023). "T2 high asthma is primarily driven by cytokines (IL-4, IL-5, IL-13), eosinophil alarmins (IL-25, IL-33, thymic stromal lymphopoietin [TSLP]), and Immunoglobulin E (IgE)." (PMID 37189529, 2023). "Regarding eosinophilic asthma, several biologics targeting IL-5, mepolizumab or its receptor, benralizumab have recently been approved and showed reduced asthma exacerbation." (PMID 37684679, 2023). "Biologic therapies for asthma include anti-IL-5 (mepolizumab) and anti-IL-5R (benralizumab), which neutralize IL-5 signaling." (PMID 37445635, 2023). "Our in vivo experiments further confirmed that autophagy was activated in OVA-induced asthma models, and the application of autophagy inhibitor CQ significantly reversed Th2 cytokines release (IL-5/IL-13), airway resistance and remodeling." (PMID 37674165, 2023). "In our case series anti-IL5 monoclonal antibodies proved efficient asthma-controlling and corticosteroid-sparing agents." (PMID 37654647, 2023). "Paradoxically, autophagy protein expression is increased in the peripheral blood of patients with severe asthma and IL-5 induces autophagy to promote the production of eosinophil cationic protein and eosinophil airway inflammation." (PMID 37090692, 2023). "Abnormal T-helper type 2 (Th2) inflammation is the most important pathological process in asthma, mediated by Th2 cytokines such as interleukin (IL)-5, IL-4, and IL-13." (PMID 37174726, 2023). "For example, anti-asthma monoclonal antibodies against pro-allergic immunoglobulin E (IgE), IL-5, IL-4, and IL-13 have been developed." (PMID 36865540, 2023). "Response of CRSwNP in patients with severe asthma was compared using dupilumab or anti-IL5/IL5R therapy." (PMID 38033455, 2023). "In another instance, Mepolizumab, a humanized antibody targeting interleukin-5, significantly decreased serum galectin-10 levels and therefore reduced the number of serum eosinophils and the frequency of severe asthma." (PMID 36838965, 2023). "Patients with CRSwNP and comorbid asthma demonstrate IgE-mediated release of immune mediators and upregulation of type 2 cytokines (IL-4, IL5, and IL-13) in the upper and lower airways." (PMID 37464395, 2023).
asthma (continued). "Drugs currently used in the treatment of asthma such as dexamethasone, montelukast, and anti-IL-5 and anti-IgE antibodies are involved in the inhibition of autophagy." (PMID 37627282, 2023). "The development of new anti-interleukin-5 (IL5) biological therapies, such as mepolizumab and benralizumab, for managing asthma represents a major advance in addressing it." (PMID 36768331, 2023). "The synergistic action of IL-4, IL-5, and IL-6 can stimulate the change of IgA secretion and mediate delayed asthma reaction." (PMID 38077793, 2023). "IL-13 and IL-5 secretion by PBMCs from patients with asthma were also negatively correlated with the plasma levels of α-MSH." (PMID 37699899, 2023). "For example, mepolizumab, a humanized, anti-interleukin-5 monoclonal antibody, has been approved for the treatment of patients with severe asthma, hypereosinophilic syndrome, EGPA, and chronic rhinosinusitis with nasal polyps." (PMID 37605658, 2023). "IL-4 is secreted by activated Th2 cells and plays an important role in airway inflammation in asthma, It induces the maturation of B lymphocytes to produce IgE under the synergistic effect of IL-5." (PMID 37451839, 2023). "Mepolizumab, an IgG1 antibody directed against IL-5, was approved in 2015 as the first anti-IL-5 biologic for add-on maintenance therapy in patients with severe asthma." (PMID 38203353, 2023). "“Type-2-high” asthma is characterized by high secretion of interleukin (IL)-4, IL-5, and IL-13, elevated eosinophil counts, serum periostin, and total IgE, including allergic and eosinophilic asthma." (PMID 37377958, 2023). "Mepolizumab, a humanized monoclonal antibody targeting IL-5, was developed in the late 1990s, and the results of its first clinical trial for asthma were published in 2000." (PMID 37179316, 2023). "We present a single-centre’s experience of 500 patient years on anti-IL-5 monoclonal antibody exposure therapy for severe asthma." (PMID 38114196, 2023). "Gene set enrichment analysis (GSEA) showed enrichment in asthma pathways, including increased IL-13, IL-4, and IL-5 expression." (PMID 37699899, 2023). "A multidisciplinary task force of asthma experts’ recommendations even recently suggested using a blood eosinophil count cut-off point of ≥150 cells/μL as an anti-IL-5 initiation guide in adults with severe asthma and a history of prior asthma exacerbations." (PMID 36675006, 2023). "Eosinophil production and survival is controlled partly by interleukin-5: anti-interleukin-5 agents reduce asthma and response correlates with baseline eosinophil counts." (PMID 35537820, 2023). "We investigated the efficacy and safety of anti-interleukin (IL)-5/IL-5 receptor α chain (Rα) monoclonal antibodies (mAbs) in patients with ABPA complicated by asthma." (PMID 37015988, 2023). "Currently, three classes of monoclonal antibodies targeting type 2 inflammation pathways are available in Italy for the treatment of severe asthma: anti-IgE (Omalizumab), anti-IL-5/anti-IL-5Rα (Mepolizumab and Benralizumab), and anti-IL-4Rα (Dupilumab)." (PMID 37298514, 2023). "Following viral infections, concentrations of sputum IL-4 and IL-5 in the asthma subjects significantly increased up to day 3, and afterwards peaked on day 8 during the observation period." (PMID 37865742, 2023). "After 18 months, anti-IL5 mepolizumab was added to omalizumab because of the increased blood eosinophil count and worsening of asthma symptoms." (PMID 38003909, 2023). "Numerous asthma cases have reported increased interleukin-4 (IL-4) and interleukin-5 (IL-5 levels, eosinophils-mediated infiltration and activated mast cells." (PMID 38178983, 2023). "In humans, levels of EETs in BALF were significantly higher in adult asthmatics than in healthy controls and were positively correlated with levels of type 2 cytokines (i.e., IL-4, IL-5, and IL-13) and asthma severity, while negatively correlated with FEV1%." (PMID 37752512, 2023).
asthma (continued). "The essential role of the Th2 type of inflammation in asthma exacerbation emerges from clinical trials of “biological” agents, such as IgE, IL-4, IL-5, and IL-13 inhibitors." (PMID 38248721, 2023). "Serum IL-5 or IL-25 levels are more highly correlated with disease activity in patients with active EGPA than in those with asthma, and in these patients they are significantly higher than in healthy controls." (PMID 37179316, 2023). "The novel immunologic agents (e.g., anti-IL-4 monoclonal antibody, anti-IL-5 monoclonal antibody, anti-IgE monoclonal antibody) are also useful in this type of asthma." (PMID 37090692, 2023). "Interleukin (IL)-4, IL-5 and IL-13, plays a vital role in the pathophysiology of eosinophilicairway diseases such as asthma, chronic rhinosinusitis, eosinophilic granulomatosis with polyangiitis and hypereosinophilic syndrome." (PMID 37886149, 2023). "Here we present an audit from a large, single-centre’s severe asthma service which looks for the prevalence of RA across all patients being treated with mepolizumab and benralizumab, two commonly used anti-IL-5 therapies." (PMID 38114196, 2023). "The simultaneous administration of omalizumab and an anti-IL5 biologic agent was the most commonly used combination in real-life studies for the treatment of severe, uncontrolled asthma." (PMID 38003909, 2023). "Omalizumab, an anti‐IgE monoclonal antibody in asthma, is now used routinely for the treatment of allergic bronchopulmonary aspergillosis, and further agents targeting IL‐4 and IL‐5 are being evaluated." (PMID 36403106, 2023). "Another review demonstrated that abnormal expression of miRNAs (miR-146a and miR-106b) was related to the production of Th2 cytokines (IL-5 and IL-13), which are both involved in the pathogenesis of asthma in children." (PMID 37629446, 2023). "Increasing the abundance of these genera can improve microbial dysbiosis, regulate the diversity of intestinal microbiota, reduce the levels of inflammatory factors, namely, IL-4, IL-5, and IL-13, and alleviate the development of asthma airway inflammation." (PMID 36636604, 2023). "Interleukin-5 plays an essential role in the recruitment of eosinophils to the airways, and today, anti-IL-5 and anti-immunoglobulin E (IgE) monoclonal antibodies are already used to reduce the exacerbation of asthma." (PMID 37511021, 2023). "From a pathophysiological view, both disorders, CRSwNP, and asthma share the same type 2 immunopathology (involvement of IgE, eosinophils, interleukin-4 (IL-4)/IL-13, and IL-5) and exhibit epithelial barrier dysfunction." (PMID 37464395, 2023). "Th2 cells and the cytokines they secrete (IL-4, IL-5, IL-13, and IL-9) are responsible for most of the pathological changes seen in asthma." (PMID 37174726, 2023). "EAACI established a blood eosinophil cut-point of ≥150/μL for a conditional recommendation to guide anti-IL-5 initiation in adult patients with severe asthma." (PMID 37174726, 2023). "The entire search strategy included the terms "mepolizumab," "anti-IL-5", "anti-interleukin 5", "eosinophilic asthma," "severe asthma," "exacerbations," and related synonyms combined by using Boolean operators." (PMID 38161547, 2023). "The IFN-γ/IL-4 and IFN-γ/IL-5 ratios of the asthma patients with AURVIs on day 1 were remarkably higher than those in asthma alone group." (PMID 37865742, 2023). "In the literature, some studies have analyzed the course of ECP during therapy with anti-IL-5/5R mAbs approved for severe asthma (e.g., mepolizumab, benralizumab)." (PMID 37763288, 2023). "Eosinophils and CD4+ cells producing IL-5 are frequently found in the blood and lung lavage fluid of patients with asthma." (PMID 38203353, 2023). "GATA-3 is known to regulate IL-5 expression which is responsible for eosinophilic inflammation in asthma." (PMID 37316684, 2023).